ADGRE4P (adhesion G protein-coupled receptor E4, pseudogene)
Description:
May mediate the cellular interaction between myeloid cells and B-cells.
Synonyms: PGR16; formerly GPR127; EMR4; EMR4P
Gene: Transcribed unprocessed pseudogene on chromosome 19 (6,954,659 to 6,990,798, reverse strand). Ensembl gene ENSG00000268758.
Subcellular location: Cell membrane (Isoform 1); Secreted (Isoform 2)
Diseases named in the same sentence as ADGRE4P in open-access papers:
ADGRE4P is named in the same sentence as 6 diseases in open-access papers, as found by Europe PMC text mining. Sharing a sentence is not in itself a finding about the gene and the disease.
ADGRE4P shares sentences with these, for which no sentence is quoted: asthma (3 papers); dermatitis (2); rhinitis (2); allergic reaction (1); inflammation (1); tumor (1).